HMGB1 (high mobility group box 1)
Diseases named in the same sentence as HMGB1 in open-access papers (continued):
Sharing a sentence is not in itself a finding about the gene and the disease.
lupus nephritis (34 papers, 2011 to 2025). Glomerulonephritis in the context of systemic lupus erythematosus. "Pearson correlation analysis showed that the serum HMGB1 levels were positively correlated with kidney score (r = 0.6583, P = 0.0022), indicating that HMGB1 levels were significantly associated with the severity of lupus nephritis." (PMID 26078984, 2015). "Initial reports described extracellular HMGB1 in cutaneous lesions, but, more recently, this DNA-binding protein has been linked to lupus nephritis —where HMGB1 has been suggested as a novel urine biomarker for nephritis activity." (PMID 23248629, 2012). "Furthermore, HMGB1 from the NETs of neutrophils was positively associated with the progression of lupus nephritis." (PMID 35250993, 2022). "HMGB1 has been implicated in the pathogenesis of kidney diseases in patients with lupus nephritis and antineitrophil cytoplasmic antibody-associated vasculitis with renal involvement, and also has been shown to promote granulomatous nephritis in an adenine-fed rat model." (PMID 21548924, 2011). "Local concentrations of HMGB1 are elevated in lupus nephritis (LN), and urinary HMGB1 has been shown to distinguish patients with active LN from those with inactive disease and healthy controls." (PMID 40877572, 2025). "HMGB1 has been found to play an important role in mediating inflammation and has been implicated in multiple disease phenotypes in SLE, including lupus nephritis and NPSLE." (PMID 39337564, 2024). "Studies outline that HMGB1 exhibits a regulatory role in driving onset and progression of secondary renal damage like glomerulonephritis, diabetic nephropathy and lupus nephritis." (PMID 39840112, 2024). "HMGB1 has been associated with multiple disease phenotypes in SLE, including lupus nephritis, neuropsychiatric lupus, and skin lesions." (PMID 37143669, 2023). "Of interest, the galectin-3 binding protein (G3BP)+ EV and urinary high-mobility group box 1 molecule (HMGB1)+ EV seem to be involved in lupus nephritis pathogenesis." (PMID 33919576, 2021). "Extracellular HMGB1 facilitates self-DNA induced macrophage activation via promoting DNA accumulation in endosomes and contributes to the pathogenesis of lupus nephritis." (PMID 33925132, 2021). "HMGB1 provoked self-DNA-induced macrophage activation by facilitating DNA accumulation in endosomes, which was involved in the development of lupus nephritis." (PMID 33925132, 2021). "The role of HMGB1 in lupus nephritis (LN) illustrates its central role in linking the innate and adaptive aspects to cause the disease phenotype." (PMID 32536928, 2020). "HMGB1 overexpression in mice resulted in an increased macrophage proinflammatory cytokine response and increased severity of lupus nephritis, whereas administration of glycyrrhizin, a blocker of HMGB1 had an opposite effect." (PMID 32536928, 2020). "HMGB1 activity is implicated in multiple disease phenotypes in SLE, including lupus nephritis and neuropsychiatric lupus." (PMID 32536928, 2020). "The monoclonal antibody 2G7 binds to the HMGB1 epitope containing aa 53-63 and has shown beneficial therapeutic effects in experimental models of arthritis, lupus nephritis (LN) and drug-induced liver injury." (PMID 32660524, 2020). "It has been proposed that the presence of HMGB1 in NETs can prevent their clearance through inhibition of DNAse I activity, leading to lupus nephritis, a complication of SLE." (PMID 31379812, 2019). "The anti-HMGB1 monoclonal antibody demonstrated therapeutic potential against albuminuria in lupus nephritis by inhibiting neutrophil recruitment and neutrophil extracellular traps." (PMID 28649578, 2017). "Particularly in lupus nephritis, HMGB1 levels were shown to be significantly elevated, correlating also with clinical features like proteinuria and SLEDAI scores." (PMID 26854151, 2015).
lupus nephritis (continued). "Next, in a group with SLE children, we had four patients presenting with lupus nephritis who also had higher levels of HMGB1 (the median concentrations were 36372,97 and 7013,95 pg/ml)." (PMID 25516724, 2014). "However, the HMGB1 inhibitor ethyl pyruvate (EP) can inhibit HMGB1 and improve lupus nephritis, leading to a reversal of senescence in MSCs." (PMID 38111850, 2023). "However, quercetin reversed the expression of IL-6, IL-8, IL-33, and HMGB1 induced by IL-33, indicating that quercetin exerts anti-fibrotic and anti-inflammatory effects in the cellular model of lupus nephritis, as opposed by IL-33." (PMID 36421424, 2022). "In patients with lupus nephritis (LN), HMGB1 induced proliferation of glomerular mesangial cells through TLR2, and HMGB1+ microparticles of urine could distinguish active and inactive LN." (PMID 35250993, 2022). "In addition, extracellular HMGB1 was shown to be a source of NET as evidence that HMGB1 levels was high to greater certain among lupus nephritis." (PMID 33925132, 2021). "Taken together, our data showed that HMGB1 in SLE bone marrow inflammatory microenvironment could promote the senescence of MSCs via TLR4/NF-κB signaling pathway, and inhibiting HMGB1 by EP could improve lupus nephritis and reverse the senescence signs." (PMID 31303606, 2019). "Interestingly, our patients presenting with lupus nephritis were also characterized by high levels of HMGB1, with statistical significance." (PMID 25516724, 2014). "Furthermore, HMGB1 in the inflammatory BM microenvironment can promote the senescence of MSCs via the TLR2/4 and NF-κB signaling pathways, and inhibition of HMGB1 by ethyl pyruvate (EP) can improve lupus nephritis and reverse senescence-associated secretory phenotype (SASP) development." (PMID 32660524, 2020). "NETs are confirmed as a source of HMGB1 in SLE patients and are positively correlated with disease progression in lupus nephritis." (PMID 32536928, 2020). "Moreover, they establish HMGB1, TLR4, and MYD88 as novel molecular markers for NETs-mediated renal inflammatory damage in lupus nephritis, providing new targets for the prevention, diagnosis, and treatment of this condition." (PMID 41208960, 2025). "Nevertheless, other study indicated that blocking of HMGB1 by the neutralizing antibody did not affect lupus nephritis in MRL/lpr mice." (PMID 31303606, 2019). "Our anti-HMGB1 mAb failed to improve lymphadenopathy; nevertheless, it demonstrated therapeutic potential against albuminuria in lupus nephritis by inhibiting neutrophil recruitment and NETs without altering autoantibody production." (PMID 28649578, 2017). "In lupus nephritis, only extracellular but not intracellular HMGB1 was shown to induce pathologic immune response (macrophage activation) against self-DNA by promoting its accumulation in endosomes and TLR-9 activation." (PMID 26854151, 2015). "Interestingly, despite increased renal tissue expression and serum HMGB1 levels in lupus nephritis, HMGB1 expression in the serum and tissues did not decrease after immunosuppressive therapy." (PMID 38481996, 2024). "Thus, in both B6/lpr and IL-17RA KOL/lpr mice there was no induction of lupus nephritis which suggests that there is no direct involvement of HMGB1 and potential immune complex formation with anti-HMGB1 in driving nephritis in these models." (PMID 30858513, 2019). "Moreover, there can be an increase in HMGB1 serum levels from patients with pedriatic lupus nephritis in comparison to SLE patients without renal involvement." (PMID 31379812, 2019). "In this study, we firstly demonstrated that inflammatory factor HMGB1 in SLE bone marrow microenvironment could promote the senescence of MSCs via TLR4/NF-κB signaling pathway, and inhibiting HMGB1 by EP could improve lupus nephritis and reverse the senescence signs of MSCs." (PMID 31303606, 2019).
lupus nephritis (continued). "Moreover, patients with active lupus nephritis present higher HMGB1 levels in urine compared with SLE patients without active nephritis and with controls." (PMID 24007972, 2013). "However, the local expression of HMGB1 in active lupus nephritis (LN) is not known." (PMID 22348591, 2012).
osteoarthritis (34 papers, 2005 to 2026). A noninflammatory degenerative joint disease occurring chiefly in older persons, characterized by degeneration of the articular cartilage, hypertrophy of bone at the margins and changes in the synovial membrane. "A similar effect was produced by the application of HBO in rabbits with osteoarthritis, where a reduction in HMGB1 expression in chondrocytes was noted." (PMID 40243713, 2025). "Chrysin exerted a protective effect on human osteoarthritis chrondrocytes by suppressing high-mobility chromosomal protein (HMGB1)." (PMID 38612781, 2024). "The articles were searched as follows: “HMGB1” AND “osteoarthritis”; “S100 b protein human” AND “osteoarthritis”; “Interleukin-33” AND “osteoarthritis”." (PMID 37569519, 2023). "IHC staining of synovial tissue unveiled an elevated expression of HMGB1 in osteoarthritis patients, particularly in cases classified as radiographically severe osteoarthritis (Kellgren/Lawrence classification > 2)." (PMID 38124066, 2023). "This study provides compelling evidence for the pivotal role of NOD2 in OA pathogenesis, demonstrating its capacity to mitigate osteoarthritis by attenuating HMGB1-induced synovial macrophage activation." (PMID 38124066, 2023). "For example, Meng et al21 reported that overexpression of PVT1 aggravates the LPS-induced osteoarthritis inflammation by regulating the HMGB1/TLR4 axis and NF-κB pathway." (PMID 35723715, 2022). "Another study has demonstrated that miR-142-3p suppressed chondrocyte apoptosis and inflammation in osteoarthritis by targeting HMGB1." (PMID 33446250, 2021). "A recent study reported that miR-140-5p has a relatively similar role to miRNA-410-3p, which is that it affects chondrocyte proliferation, apoptosis and inflammation by targeting HMGB1 in osteoarthritis." (PMID 32709223, 2020). "Our data showed that HMGB1 was negatively correlated with CCN3 expression in IL‐1β‐induced osteoarthritis responses." (PMID 31454155, 2019). "HMGB1 was negatively correlated with CCN3 in osteoarthritis, and HMGB1 is involved in the protective effect of CCN3 in OA." (PMID 31454155, 2019). "High‐mobility group box 1 was negatively correlated with CCN3 in IL‐1β‐induced osteoarthritis responses, and HMGB1 is involved in the protective effect of CCN3 in OA." (PMID 31454155, 2019). "While symptomatic osteoarthritis is associated with an elevated level of acute phase reactants in the blood the role of TREM-1, HMGB-1, and RAGE are yet to be defined in musculoskeletal pathology." (PMID 27792788, 2016). "We have recently reported that HMGB1 is released by osteoarthritic synoviocytes after activation with interleukin-1beta (IL-1β) The present study investigated the role of HMGB1 in synovial inflammation in osteoarthritis (OA)." (PMID 20799933, 2010). "HMGB1 levels in the synovial fluid and sera of RA patients are significantly elevated as compared with levels in osteoarthritis patients." (PMID 15987483, 2005). "Additionally, their derived exosomes have been shown to inhibit inflammation in osteoarthritis through the HMGB1/TLR4/NF-κB pathway, a promising avenue for therapeutic intervention in KOA." (PMID 40636390, 2025). "Furthermore, this study tracked the usefulness of the optimized formulae to attenuate mono-iodoacetate (MIA)-induced osteoarthritis in rats via modulating HMGB-1/RAGE/NF-κB pathway, Klotho, and miRNA-499a that are implicated in the pathogenesis of OA." (PMID 38502267, 2024). "In canonical pathway analysis, most inflammation-associated signal pathways were upregulated in noTC cultured BMDMs, at both basal level and after LPS stimulation, including HMGB1 signaling, osteoarthritis pathway, p38 MAPK signaling, IL8 signaling and TREM1 signaling." (PMID 35874686, 2022). "Additionally, extranuclear HMGB1 localisation has been described in synovial tissue from osteoarthritis (OA) patients and in bovine osteoarthritic cartilage specimens." (PMID 21871094, 2011).
osteoarthritis (continued). "Moreover, canonical pathways that include NF-κB, such as Osteoarthritis Signaling (this canonical pathway set has been described as a critical regulatory element for the onset of osteoarthritis), HMGB1 signaling, or NF-κB signaling, were predicted to be inhibited." (PMID 32575510, 2020). "It was subsequently demonstrated that exosome-mediated PVT1 targets miR-93-5p, modulates the activity of the HMGB1/TLR4/NF-κB pathway, and influences the progression of lipopolysaccharide-induced osteoarthritis." (PMID 40636390, 2025). "Consistently, more subchondral bone marrow cells lost HMGB1 expression in STR/Ort mice relative to CBA mice, indicating that cellular senescence occurs at the pre- or early-osteoarthritis stage." (PMID 35881544, 2022). "In the presence of IL-1β, HMGB1 enhanced the phosphorylated p38 MAPK level and significantly potentiated NF-κB activation in SF from patients with osteoarthritis." (PMID 24302816, 2013). "Numerous studies have reported the association between HMGB1 and inflammatory diseases; however, its role in temporomandibular joint (TMJ) osteoarthritis (OA) has not been elucidated." (PMID 36906519, 2023). "Because TREM-1, HMGB-1, and RAGE affect inflammation in pathologic musculoskeletal conditions such as osteoarthritis, pharmacological manipulation of these mediators may represent a novel therapeutic approach to treat a variety of debilitating diseases." (PMID 27792788, 2016). "In human articular cartilage, HMGB1 may participate in endochondral ossification during osteogenesis and recently, the related protein HMGB2 has been involved in ageing and osteoarthritis (OA)." (PMID 20799933, 2010).
Autoimmunity (33 papers, 2012 to 2025). The occurrence of an immune reaction against the organism's own cells or tissues. "HMGB1, a representative injury-associated molecule, has been implicated in various pathological processes, including neurodegenerative diseases, autoimmunity, and cancer progression." (PMID 40148311, 2025). "Vitiligo melanocytes release multiple cytokines and danger-associated molecular patterns, such as Hsp70 and HMGB1, in response to environmental signals relevant to the initiation of autoimmunity." (PMID 36429011, 2022). "Gain- and loss-of-function analysis showed that HMGB1 exacerbated the severity of renal disease and autoimmunity in the murine model of SLE." (PMID 33807604, 2021). "Another TLR that has been implicated in inducing autoimmunity against nucleosomes is TLR2 which binds nuleosome-HMGB1 complexes." (PMID 24151519, 2013). "In the ApoE−/- mouse AS model induced by the Western diet, anti-HMGB1 antibodies were more than six times higher than regular diet ApoE−/- mice and ApoE+/+ mice, indicating that HMGB1 autoimmunity is involved in the progression of AS." (PMID 35281098, 2022). "This is reasonable, as a positive correlation between CRP levels and HMGB1 was described before (in the setting of autoimmunity and inflammation;)." (PMID 34671818, 2022). "During activation or cell death, HMGB1 can be released from various cells mediating inflammation and acting as endogenous adjuvant, thus inducing autoimmunity." (PMID 36275673, 2022). "It is therefore justified to conclude that the inhibition of HMGB1 by EP is one of the major ways in which this compound restrains chronic inflammation and autoimmunity." (PMID 34944410, 2021). "mTOR plays a crucial role in the relationship among HMGB1, activation of mDCs, and autoimmunity in SLE." (PMID 34164408, 2021). "Histological analysis of the grafts showed that islet morphology was preserved, and immunological analyses revealed that autoimmunity was suppressed in anti-HMGB1-treated mice." (PMID 32072192, 2020). "Given the critical role of DCs in type 1 diabetes-associated autoimmunity, we treated 2.5-week-old NOD mice with an HMGB1-blocking antibody." (PMID 32072192, 2020). "In autoimmunity, patient's HMGB1 levels increase in the active phase of disease, worsening inflammation and symptoms." (PMID 31379812, 2019). "Outside the cell, HMGB-1 activates the immune system acting as a chemokine or an alarmin to mediate physiological and pathological responses, such as autoimmunity." (PMID 29915590, 2018). "Blockade of HMGB1 has thus far proven to be beneficial in ameliorating a number of types of experimental autoimmunity, making its therapeutic potential very promising." (PMID 23772226, 2013). "Extracellular HMGB1 has apparently contrasting biological actions: it sustains inflammation (with the possible establishment of autoimmunity or of self-maintaining tissue damage), but it also activates and recruits stem cells, boosting tissue repair." (PMID 24710526, 2012). "The significance of autoimmunity against nuclear antigens such as histones and high-mobility group box 1 in immune regulation has been demonstrated." (PMID 22615941, 2012). "Recently, the role of HMGB1 has been demonstrated in autoimmunity and chronic inflammatory diseases, especially those with renal manifestations such as antineutrophil cytoplasmic antibody (ANCA)-associated vasculitis, chronic kidney disease (CKD) and SLE." (PMID 22892043, 2012). "HMGB1 is not only a nuclear factor regulating chromatin remodeling or DNA repair, and gene expression, but also a secreted factor eliciting inflammatory response in autoimmunity, cancer, trauma, and ischemia reperfusion injury." (PMID 38580917, 2024). "Therefore, HMGB1 interaction with scaRNAs proposes additional mechanism for the HMGB1 regulatory function in cancer, autoimmunity, as well as in many development-related processes." (PMID 38580917, 2024).